SCUBE3 (signal peptide, CUB domain and EGF like domain containing 3)
Diseases named in the same sentence as SCUBE3 in open-access papers (continued):
Sharing a sentence is not in itself a finding about the gene and the disease.
melanoma (3 papers, 2022 to 2023). A malignant, usually aggressive tumor composed of atypical, neoplastic melanocytes. "Our findings demonstrated that SCUBE3 OE partially restored melanoma angiogenesis and metastasis in DEPDC1B KD cells, implying additional factors are required." (PMID 35088579, 2022). "DEPDC1B competitively interacts with CDC16 in the cytosol to block the ubiquitination and degradation of SCUBE3, enabling stabilized SCUBE3 to be secreted from melanoma cells for blood vessel recruitment to facilitate their growth, survival, and metastasis." (PMID 35088579, 2022). "In conclusion, it is revealed that a SOX10‐DEPDC1B‐SCUBE3 regulatory axis promotes melanoma angiogenesis and metastasis, which suggests that targeting secreted SCUBE3 can be a therapeutic strategy against metastatic melanoma." (PMID 35088579, 2022). "To establish the clinical relevance of DEPDC1B and SCUBE3 on angiogenesis, we analyzed their expression in association with CD31 in a melanoma tissue microarray." (PMID 35088579, 2022). "Here, we demonstrated that SOX10 regulates expression of DEPDC1B which sequesters ubiquitin ligase CDC16 to stabilize the secreted SCUBE3 protein for promoting melanoma growth, angiogenesis, and metastasis." (PMID 35088579, 2022). "Altogether, our findings reveal a SOX10‐DEPDC1B‐SCUBE3 regulatory axis that promotes melanoma angiogenesis and facilitates its metastatic progression, suggesting the possibility of targeting secreted SCUBE3 as a therapeutic strategy against metastatic melanoma." (PMID 35088579, 2022). "Importantly, expression of SOX10, DEPDC1B, and SCUBE3 are positively correlated with microvessel density in the advanced stage of melanomas." (PMID 35088579, 2022). "To further investigate whether SCUBE3 secreted from melanoma cells contributes to angiogenesis, we designed two shRNAs to deplete SCUBE3 mRNA (SCUBE3 KD1 and KD2) and proteins, and generated lentiviral vector‐mediated SCUBE3 overexpression (SCUBE3 OE) in both WM266‐4 and A2058 cells." (PMID 35088579, 2022). "Consistent with the role of SCUBE3 in promoting angiogenesis in vitro and in vivo, a recent molecular study showed that DEP domain-containing 1B enhances melanoma angiogenesis and metastasis by stabilizing SCUBE3." (PMID 37237303, 2023). "It is worth noting that it was reported that DEPDC1B promotes SCUBE3 secretion through competitive binding with ubiquitin ligase CDC16, thus promoting angiogenesis and metastasis of melanoma." (PMID 37642235, 2023). "Altogether, these results demonstrate that SOX10 and DEPDC1B are clinically correlated with SCUBE3 and CD31 expressions in advanced stages of melanoma, consistent with their regulatory relationship in promoting melanoma angiogenesis and metastasis." (PMID 35088579, 2022). "This study unravels a new molecular mechanism of DEPDC1B acting downstream of SOX10 to promote melanoma angiogenesis and metastasis through CDC16 sequestration that stabilizes secreted SCUBE3, which suggests the possibility of targeting SCUBE3 as a therapeutic strategy against metastatic melanoma." (PMID 35088579, 2022). "In addition, melanoma cells treated with SCUBE3 KD1 and KD2 exhibited marked reductions in proliferation, number of colonies formed, and invasive capacity compared with the scramble control, which further consolidates the oncogenic role of SCUBE3 in melanoma." (PMID 35088579, 2022). "In contrast to other cancer types, the ability of DEPDC1B to enhance the metastatic potential of melanoma does not dependent on the activities of Rho GTPase signaling and canonical Wnt signaling, but involves the secretion of SCUBE3, which was shown to promote angiogenesis in vitro and in vivo." (PMID 35088579, 2022). "In addition, immunofluorescence staining in melanoma tissue arrays showed that expression levels of SOX10, DEPDC1B and CDC16 were high in nevi which do not metastasize but SCUBE3 was barely detectable." (PMID 35088579, 2022).
autoimmune disease (1 paper, 2020). A disorder resulting from loss of function or tissue destruction of an organ or multiple organs, arising from humoral or cellular immune responses of the individual to their own tissue constituents. "SCUBE3 was associated with autoimmune diseases such as psoriasis and rheumatoid arthritis." (PMID 33274247, 2020). "As a TGF-β signaling activator, additional studies are needed to evaluate the value of targeting SCUBE3 for autoimmune disease therapy." (PMID 33274247, 2020). "Because our knowledge of SCUBE3 biological function in autoimmune disease remains limited, future biological studies on lupus-prone mice might provide more detailed information and carry out essential clues for SCUBE3 in the pathogenesis of SLE." (PMID 33274247, 2020).
brain tumours (1 paper, 2022). "Our data suggest that H3.3G34W may regulate the expression of SCUBE3 by altering the balance between H3K27ac and H3K27me3 at its proximal enhancer region: these data are in keeping with recent work which shows a gain in H3K27me3 in G34R-mutated brain tumours as well as in GCT cell lines." (PMID 36138226, 2022).
breast tumor (1 paper, 2021). "In addition, the expression of SCUBE3 in breast tumor tissues was confirmed by immunohistochemistry." (PMID 34006286, 2021).
Crohn disease (1 paper, 2020). A gastrointestinal disorder characterized by chronic inflammation involving all layers of the intestinal wall, noncaseating granulomas affecting the intestinal wall and regional lymph nodes, and transmural fibrosis. "Although the study has unveiled the genetic association of SCUBE3 with serum Vit D levels in Crohn's Disease (CD) patients, the association between variants in the SCUBE3 gene and SLE susceptibility has not yet been elucidated." (PMID 33274247, 2020).
liver cancer (1 paper, 2022). An epithelial or non-epithelial malignant neoplasm that arises from the liver. "Female sex, older age, and higher body weight correlated with a significantly higher expression of SCUBE3 in liver cancer tissues." (PMID 34980127, 2022). "The results of the two apoptosis detection experiments showed that CCNE1 overexpression reverses the influence of SCUBE3 knockdown on the apoptosis of liver cancer cells." (PMID 34980127, 2022). "To verify how SCUBE3 promotes the proliferation of liver cancer cells through CCNE1, we first applied KEGG enrichment analysis on the DEGs in the classical pathway screened by Affymetrix GeneChip microarray analysis." (PMID 34980127, 2022).
lupus (1 paper, 2020). "Our research revealed that variants in SCUBE3 can be considered as a new genetic susceptibility factor for systemic lupus erythematosus." (PMID 33274247, 2020). "Our research revealed that variants in SCUBE3, which encode SCUBE3 as a TGF-β signaling activator, can be considered as a new genetic susceptibility factor for systemic lupus erythematosus." (PMID 33274247, 2020).
lymph node metastasis (1 paper, 2021). "In addition to SCUBE3 expression, significant factors associated with the risk of death were patient age (p = 0.0025), histologic grade (p = 0.0422), lymph node metastasis (p = 0.0123), TMN stage III (p = 0.0055), ER expression status (p = 0.0023), and TNBC subtype (p = 0.0189)." (PMID 34006286, 2021).
metastatic melanoma (1 paper, 2022). A melanoma that has spread from its primary site to another anatomic site. "As expected, CDC16 was ubiquitously expressed in all the analyzed specimens, but we detected a positive correlation between SOX10 and SCUBE3 expressions in metastatic melanomas (n = 19/22)." (PMID 35088579, 2022).
renal failure (1 paper, 2020). "Whether the expression of rs1888822 SCUBE3 was affected by the disease conditions such as high creatinine/renal failure was interesting and well worth to be investigated in separated projects in the future." (PMID 33274247, 2020).
small cell lung carcinoma (1 paper, 2022). Small cell lung cancer (SCLC) is a highly aggressive malignant neoplasm, accounting for 10-15% of lung cancer cases, characterized byrapid growth, and early metastasis. "In non-small-cell lung cancer, SCUBE3 is reported to bind to type 2 TGFβ receptor (TGFβIIR) to activate the TGFβ pathway." (PMID 34980127, 2022).
tumor (13 papers, 2020 to 2023). "Tumour methylation of SCUBE3 also was associated with a significantly increased risk of death and cancer relapse." (PMID 37580336, 2023). "A study reported that SCUBE3 tumor methylation was significantly associated with increased risk of cancer relapse and cancer-related death." (PMID 36142489, 2022). "The association between SCUBE3 expression level and tumor prognosis was analyzed using clinical data of these patients and Kaplan–Meier analysis." (PMID 34006286, 2021). "We also found enrichment for other tumor progression-related processes such as cell migration and Wnt signaling (examples of differentially expressed genes: SCUBE3, SEMA3C, WNT2)." (PMID 37085135, 2023). "SCUBE3 expression in tumour tissue was upregulated compared with that in the adjacent normal tissue." (PMID 34980127, 2022). "SCUBE3 transcription levels in primary tumor tissue were significantly higher than normal subjects (p ≤ 1.62E-12)." (PMID 34006286, 2021). "We studied the expression pattern of SCUBE3 using the Tumor Immune Estimation Resource (TIMER) and UALCAN databases, and verified the results by immunohistochemical staining." (PMID 34006286, 2021). "We first conducted a comprehensive study on the expression pattern of SCUBE3 using the Tumor Immune Estimation Resource (TIMER) and UALCAN databases." (PMID 34006286, 2021). "As expected, we observed an increase in the levels of markers that are important for immune responses and inflammation (Saa1, Saa2, Lcn-2, Ltf, and Orosomucoid-2) and initiating and promoting tumor growth (Ighg1, Scube3, and Fgl1)." (PMID 33110211, 2020). "Overexpression of SCUBE3 may weaken the killing effect of the immune system on tumors and eventually lead to tumor metastasis, which plays the greatest role in the increase of risk score and may provide some directions for related fields." (PMID 35663937, 2022). "This is in line with a relatively low level of SCUBE3 expression in DEPDC1B+ primary tumor samples." (PMID 35088579, 2022). "Previous studies have shown that MMPs could promote tumor invasion, metastasis, and angiogenesis after SCUBE3 was knocked out." (PMID 34006286, 2021). "SCUBE3 knockdown expression reduced the metastatic potential of NSCLC and tumor growth in an in vivo model." (PMID 36142489, 2022). "So far, no studies have shown that these seven genes (IGHG2, PODXL2, LRRC17, GABRA3, SCUBE3, HLF and RFLNB) are directly related to pyroptosis in tumor cells." (PMID 36155774, 2022). "The results showed that compared with HSKMC, PODXL2, LRRC17, GABRA3, SCUBE3, and RFLNB were highly expressed in tumor cells, while IGHG2 and HLF were low expressed." (PMID 36155774, 2022). "It has been found that the fragments released by MMP-2 and MMP-9 cleavage of SCUBE3 can bind to transforming growth factor-b (TGF-b) type II receptors, thus activating TGF-b signal transduction to promote tumor progression." (PMID 32322168, 2020). "Matrix metalloproteinase-2 (MMP-2) and MMP-9 cleavage by SCUBE3 releases fragments, which can bind to transforming growth factor-b (TGF-b) type II receptors, thereby activating the TGF-b signal transduction and promoting tumor development." (PMID 35663937, 2022). "However, in the study of the proliferation of other tumours, the biological mechanism of SCUBE3 is not accurately described." (PMID 34980127, 2022). "Consistent with our in vitro results, SCUBE3 mRNA was virtually absent in GCT samples and in other osteoclast-rich tumours." (PMID 36138226, 2022).
cancer (9 papers, 2013 to 2023). A tumor composed of atypical neoplastic, often pleomorphic cells that invade other tissues. "Very little literature exists on polymorphisms in SCUBE3 but this gene appears to be associated with hypermethylation in some cancers." (PMID 24084050, 2013). "SCUBE3 appears to be associated with hypermethylation in some cancers, and is associated with the VDR pathway." (PMID 24084050, 2013). "In addition to the associations of aberrant SCUBE3 expression with pathogenesis and clinical outcomes of various types of cancers, mutations in SCUBE3 (GenBank: NM_152753) are associated with human skeletal disease." (PMID 37237303, 2023). "Because enhancement of TGF-β signaling by SCUBE3 has been linked to a variety of cancers, understanding the molecular and structural basis of enhancement action could facilitate the development of more effective cancer therapy." (PMID 37237303, 2023). "We found that the expression of SCUBE3 was associated with cancer stage and different subtypes." (PMID 34006286, 2021). "We found that knockdown of SCUBE3 expression was associated with inhibition of cancer cell proliferation MTT, colony formation assay and EdU assays were performed to investigate the effects of silencing of SCUBE3 on HCC cell proliferation in vitro." (PMID 34980127, 2022). "Accumulating evidences indicate that the signal peptide-CUB-EGF-like domain-containing protein 3 (SCUBE3) plays a key role in the development and progression of many human cancers." (PMID 34006286, 2021). "An analysis of individual cancer status showed that SCUBE3 expression in stage 2 was significantly higher than that in stage 1 (p = 2.87E-02), and that in stage 3 was significantly higher than that in stage 2 (p = 1.26E-02)." (PMID 34006286, 2021). "The expression of SCUBE3 in multiple cancer types (n = 32) was analyzed by the TIMER database." (PMID 34006286, 2021). "Compared with the early stage, the expression of SCUBE3 is higher in late-stage cancers, which indicates that SCUBE3 may play a role in cancer progression and invasion." (PMID 34006286, 2021). "Furthermore, the representative immunohistochemical staining patterns for SCUBE3 were analyzed, SCUBE3 staining was primarily seen in the cytoplasm of cancer cells, while nuclear staining was also observed in ~ 30% of cancer cells." (PMID 34006286, 2021). "Therefore, we speculate that SCUBE3 may be related to the occurrence and development of cancer." (PMID 34006286, 2021). "SCUBE3 is an endogenous TGF-β receptor ligand, and knockdown of SCUBE3 expression also suppressed tumorigenesis and cancer metastasis in vivo in lung cancer." (PMID 32764572, 2020).
skeletal disease (2 papers, 2021 to 2023). "Subsequently, another team identified different recessive SCUBE3 mutations in a patient with undiagnosed skeletal disease." (PMID 37237303, 2023). "The implication of SCUBE3 as a skeletal disease-causing gene was supported by our identification of mice homozygous for the Scube3C301Y allele developing severe skeletal defects." (PMID 34142127, 2021). "To identify additional patients with skeletal disease potentially attributable to mutations in SCUBE3, we queried the Baylor Genetics Laboratory database, which includes nonsynonymous variants identified from clinical exome sequencing and clinician-provided clinical synopses." (PMID 34142127, 2021). "However, during the course of this study, multiple subjects with recessive SCUBE3 mutations were reported with short stature, oral-facial abnormalities, skeletal abnormalities and, although variable, spine deformity, suggesting a novel SCUBE3-associated skeletal disease." (PMID 34142127, 2021).
SCUBE3 also shares sentences with these, for which no sentence is quoted: gastric cancer (2 papers); Paget disease of bone (2); sarcoma (2); bladder carcinoma (1); bladder urothelial carcinoma (1); bone tumour (1); cervical squamous cell carcinoma (1); chordoma (1); Diamond-Blackfan anemia (1); esophageal adenocarcinoma (1); growth disorders (1); head–neck squamous cell carcinoma (1); kidney chromophobe (1); lung adenocarcinoma (1); metabolic bone disorder (1); non-small cell lung carcinoma (1); ovarian carcinoma (1); pancreatic adenocarcinoma (1); prostate adenocarcinoma (1); stomach adenocarcinoma (1); thyroid carcinoma (1); thyroid tumours (1).